FGF23 (fibroblast growth factor 23)
Description:
Regulator of phosphate homeostasis. Inhibits renal tubular phosphate transport by reducing SLC34A1 levels. Up-regulates EGR1 expression in the presence of KL (By similarity). Acts directly on the parathyroid to decrease PTH secretion (By similarity). Regulator of vitamin-D metabolism. Negatively regulates osteoblast differentiation and matrix mineralization.
Synonyms: HYPF; ADHR; FGFN; HFTC2; HPDR2; PHPTC
Tractability: Small molecule: a structure with a bound ligand is known; a high-quality ligand is known. Antibody: an approved drug acts on it; UniProt places it where antibodies can reach, with high confidence; its Gene Ontology location is reachable by antibodies, with high confidence; UniProt predicts a signal peptide or a membrane-spanning region. PROTAC: a small molecule that binds it is known.
Target class: Secreted protein
Gene: Protein-coding gene on chromosome 12 (4,368,227 to 4,379,712, reverse strand). Ensembl gene ENSG00000118972.
Subcellular location: Secreted
Subcellular location (Human Protein Atlas): Vesicles; Centrosome; Cytosol; Nuclear bodies; Predicted to be secreted
Pathways (Reactome):
Signal Transduction: Downstream signaling of activated FGFR1; FGFR1c and Klotho ligand binding and activation; FGFR1c ligand binding and activation; FGFR2c ligand binding and activation; FGFR3c ligand binding and activation; FGFR4 ligand binding and activation; FGFRL1 modulation of FGFR1 signaling; FRS-mediated FGFR1 signaling; FRS-mediated FGFR2 signaling; FRS-mediated FGFR3 signaling; FRS-mediated FGFR4 signaling; Negative regulation of FGFR1 signaling; Negative regulation of FGFR2 signaling; Negative regulation of FGFR3 signaling; Negative regulation of FGFR4 signaling; PI-3K cascade:FGFR1; PI-3K cascade:FGFR2; PI-3K cascade:FGFR3; PI-3K cascade:FGFR4; PI3K Cascade; PI5P, PP2A and IER3 Regulate PI3K/AKT Signaling; PIP3 activates AKT signaling; Phospholipase C-mediated cascade: FGFR1; Phospholipase C-mediated cascade; FGFR2; Phospholipase C-mediated cascade; FGFR3; Phospholipase C-mediated cascade; FGFR4; RAF/MAP kinase cascade; SHC-mediated cascade:FGFR1; SHC-mediated cascade:FGFR2; SHC-mediated cascade:FGFR3; SHC-mediated cascade:FGFR4
Disease: Activated point mutants of FGFR2; Constitutive Signaling by Aberrant PI3K in Cancer; Signaling by FGFR1 in disease; Signaling by FGFR2 in disease; Signaling by FGFR3 in disease; Signaling by activated point mutants of FGFR1; Signaling by activated point mutants of FGFR3
Metabolism of proteins: Post-translational protein phosphorylation; Regulation of Insulin-like Growth Factor (IGF) transport and uptake by Insulin-like Growth Factor Binding Proteins (IGFBPs)
Gene Ontology:
Molecular function: protein binding; growth factor activity; type 1 fibroblast growth factor receptor binding; fibroblast growth factor receptor binding
Biological process: negative regulation of bone mineralization; negative regulation of osteoblast differentiation; phosphate ion homeostasis; regulation of phosphate transport; vitamin D catabolic process; fibroblast growth factor receptor signaling pathway; negative regulation of hormone secretion; neurogenesis; positive regulation of cell population proliferation; positive regulation of MAPK cascade; regulation of cell migration; calcium ion homeostasis; cellular response to interleukin-6; cellular response to leptin stimulus; cellular response to parathyroid hormone stimulus; cellular response to vitamin D; ERK1 and ERK2 cascade; positive regulation of DNA-templated transcription; positive regulation of ERK1 and ERK2 cascade; response to magnesium ion; response to sodium phosphate; vitamin D metabolic process
Cellular component: extracellular region; cytoplasm; endoplasmic reticulum lumen; Golgi lumen
Genetic constraint (gnomAD): Loss-of-function variants: 6 observed, 7.13 expected, observed/expected ratio (o/e) 0.84, 90% interval 0.46 to 1.61. That is too few expected variants to judge how well the gene tolerates losing a copy. Missense variants: 300 observed, 342 expected, observed/expected ratio (o/e) 0.88, 90% interval 0.8 to 0.96. Synonymous variants: 113 observed, 143.34 expected, observed/expected ratio (o/e) 0.79, 90% interval 0.68 to 0.92.
Homologues: Orthologues: chimpanzee FGF23 (98% identical), macaque FGF23 (96% identical), rabbit FGF23 (84% identical), dog FGF23 (78% identical), pig FGF23 (76% identical), rat Fgf23 (72% identical), guinea pig FGF23 (71% identical), mouse Fgf23 (71% identical), tropical clawed frog fgf23 (45% identical), tropical clawed frog fgf23.2 (42% identical), zebrafish fgf23 (33% identical). Paralogues in human: FGF3 (23% identical), FGF19 (22% identical), FGF21 (22% identical), FGF16 (22% identical), FGF5 (21% identical), FGF20 (21% identical), FGF9 (20% identical), FGF13 (20% identical), FGF4 (19% identical), FGF10 (18% identical), FGF14 (18% identical), FGF6 (18% identical), and 9 more.
Diseases named in the same sentence as FGF23 in open-access papers:
FGF23 is named in the same sentence as 491 diseases in open-access papers, as found by Europe PMC text mining. Sharing a sentence is not in itself a finding about the gene and the disease. The quoted sentences say what the papers report.
chronic kidney disease (577 papers, 2008 to 2026). Impairment of the renal function secondary to chronic kidney damage persisting for three or more months. "Circulating levels of fibroblast growth factor 23 (FGF23) increase early in chronic kidney disease and are associated with a faster progression and increased mortality." (PMID 41561945, 2025). "This study investigated the potential of FGF23 isoforms and the iFGF23:cFGF23 ratio as diagnostic markers for distinguishing between acute kidney injury and chronic kidney disease." (PMID 40869274, 2025). "In fact, FGF-23 was independently associated with decreased HRV in patients with chronic kidney disease (stage 5)." (PMID 40346324, 2025). "Although chronic kidney disease is a cause of raised FGF23, this latter tends to be low in FS, which led us to consider TIO with an associated FS." (PMID 39888445, 2025). "Hemodialysis patients with chronic kidney disease have a higher amount of fibroblast growth factor 23 (FGF23), which causes left ventricular hypertrophy (LVH)." (PMID 40559238, 2025). "Nonetheless, FGF-23 is considered a biomarker of cardiovascular risk, chronic kidney disease, and mortality, with evidence linking it to diabetic nephropathy progression." (PMID 40943671, 2025). "The chronic exposure to elevated levels of FGF23 have been proposed as a risk factor for cardiac morbidity, based upon its having been linked with cardiac hypertrophy in the context of chronic renal failure." (PMID 38818505, 2024). "The analysis includes the risk of cardiovascular disease for both primary and secondary causes of elevated FGF23, such as chronic renal insufficiency." (PMID 38846254, 2024). "One of the possible causes underlying the development of osteoporosis in people with chronic kidney disease is the early rise of serum fibroblast growth factor-23 levels in these patients." (PMID 38577568, 2024). "FGF23, a protein associated with cardiac hypertrophy, chronic renal disease, and vascular stiffness, emerged as a reliable predictor for AF in their study." (PMID 38846254, 2024). "FGF23-induced bone loss is a consequence of mineral and bone disorders associated with chronic kidney disease (CKD)." (PMID 38902808, 2024). "A large and growing body of literature demonstrates that chronic kidney disease promotes elevated levels of fibroblast growth factor-23 and α-Klotho deficiency, thereby increasing susceptibility to cardiovascular disease." (PMID 38792509, 2024). "Excessive levels of FGF23 have been associated with adverse effects, particularly in patients with chronic kidney disease." (PMID 38732094, 2024). "In the kidneys, elevated FGF23 levels inhibit phosphate transporters, causing phosphaturia and hypophosphatemia, as observed in patients with chronic kidney disease." (PMID 36635269, 2023). "Dysregulation of FGF23 is linked with disorders of phosphate metabolism including hypophosphataemic rickets, chronic kidney disease and tumor-induced osteomalacia." (PMID 37223031, 2023). "Our results suggest that high baseline plasma FGF23 levels in end-stage renal disease patients on chronic hemodialysis are associated with an increased risk for SARS-CoV-2 infection and severe COVID-19, including hospitalization and death." (PMID 36828412, 2023). "Elevation of circulating FGF23 in patients with chronic kidney disease has been associated with increased risk of cardiovascular disease, including AF, by promoting cardiac remodelling." (PMID 37798357, 2023). "The bone-derived hormone fibroblast growth factor-23 (FGF23) has recently received much attention due to its association with chronic kidney disease and cardiovascular disease progression." (PMID 37992803, 2023). "Because of the overlapping sites of action of insulin and FGF23 in the kidneys, attempts have been made to evaluate the association of FGF23 with insulin resistance in patients with advanced stages of chronic kidney disease." (PMID 38139126, 2023).
chronic kidney disease (continued). "Our data suggested that abnormally high expression of FGF23 and D-serine increases the risk of developing hearing damage in chronic renal failure." (PMID 36649363, 2023). "The level of FGF23 in CKD patients is an independent risk factor for a progression to end-stage renal disease (ESRD) and is associated with cardiovascular- and all-cause mortality." (PMID 37932788, 2023). "In recent years, FGF23 has gained significant interest due to its strong association with poor prognosis in chronic kidney disease and cardiovascular disease." (PMID 37992803, 2023). "FGF23 was initially found to be a regulator of phosphate and vitamin D metabolism, and was also shown to be associated with various genetic disorders and chronic kidney disease." (PMID 37593148, 2023). "Elevated FGF-23 level was found to be an independent risk for fragility fractures in elderly patients as well as in patients with chronic renal failure." (PMID 37065752, 2023). "FGF23 is a major regulator of phosphaturia and its gene expression in the bone is upregulated during acute and chronic kidney disease; however, the underlying mechanisms are complex and only partially understood (recently reviewed in Agoro and White, (2023))." (PMID 36967231, 2023). "Several previous studies have shown that the circulating FGF23 concentration is not only associated with cardiac complications in patients with chronic kidney disease but is also independently associated with cardiac disease." (PMID 37593148, 2023). "Studies in chronic kidney disease (CKD) patients have shown that elevated FGF23 levels are independently associated with CKD progression, left ventricular (LV) hypertrophy, cardiovascular risk, and all-cause mortality." (PMID 35884995, 2022). "The serum level of FGF-23 is increased due to hyperphosphatemia in patients with renal failure and is associated with a high risk of mortality in patients with chronic kidney disease." (PMID 35386950, 2022). "While there are known associations of elevated FGF-23 and cardiovascular morbidities in chronic kidney diseases in both clinical and experimental studies, less is understood in an acute, hyperadrenergic setting." (PMID 35622651, 2022). "Serum FGF23 levels are increased in chronic kidney disease in direct proportion to the loss of renal function." (PMID 35231062, 2022). "Elevated serum FGF23 concentration is a potential prognostic marker of chronic kidney disease, and is associated with dementia and AD." (PMID 35928129, 2022). "In other studies, high FGF-23 concentrations in human patients suffering from chronic kidney disease has been implicated in the pathogenesis of left-ventricular hypertrophy." (PMID 35484585, 2022). "In patients with chronic kidney disease, serum FGF23 concentration is associated with iron deficiency, which increases cardiomyocyte injury and leads to systemic inflammatory responses." (PMID 35912897, 2022). "In diseases characterized by excessive FGF23 secretion such as X-linked hypophosphatemia or chronic kidney disease, enhanced FGF23 signaling suppresses 1,25(OH)2D production in the kidney." (PMID 36501215, 2022). "FGF23 is also associated with left ventricular hypertrophy in chronic kidney disease patients and, therefore, it is critical to control circulating FGF23, PTH, and mineral levels." (PMID 35176038, 2022). "As the estimated glomerular filtration rate decreases, a corresponding increase in FGF-23 can be seen, and levels of FGF-23 have appeared to predict risk of death in patients with chronic kidney disease." (PMID 35159318, 2022). "Early stages of chronic kidney disease are associated with increased FGF23 levels and hyperphosphaturia." (PMID 34659120, 2021). "High circulating FGF23 levels are associated with increased mortality in patients with chronic kidney disease and those on dialysis." (PMID 33000285, 2021).
chronic kidney disease (continued). "As FGF23 is known to cause impaired bone mineralization in MDS and chronic kidney disease, and as it also acts as a negative regulator of erythropoiesis in vivo, we analyzed FGF23 expression in Ctnnb1OE-SEC mice in more detail." (PMID 34845225, 2021). "High serum concentrations of phosphate and linked parameters of phosphorus homeostasis, such as parathyroid hormone (PTH) and fibroblast growth factor 23 (FGF-23), are associated with increased morbidity and mortality in patients with chronic kidney disease." (PMID 34944233, 2021). "Investigations in 3070 patients of the Chronic Renal Insufficiency Cohort (CRIC) study with a median eGFR of 42 ml/min/1.73 m2 demonstrate an independent association of high circulating FGF23 with LVH." (PMID 34536161, 2021). "Results of studies investigating the association between fibroblast growth factor-23 (FGF23) levels, fat mass and/or adipokine profile in patients with chronic kidney disease." (PMID 34422722, 2021). "Several reports show that elevated levels of FGF23 are associated with increased risk of left ventricular hypertrophy and increased left-ventricular mass index in elderly subjects, both with chronic kidney disease (CKD) patients and healthy subjects." (PMID 34572066, 2021). "At the early stage of patients with chronic kidney disease, the decrease of Klotho level will cause a compensatory increase in FGF23." (PMID 34901023, 2021). "Fibroblast growth factor-23 (FGF23) is a diagnostic biomarker for chronic kidney disease (CKD) and a pathogenic contributor to CKD progression." (PMID 34721981, 2021). "The increase of FGF23 can be used as a risk factor for CVD in patients with end-stage renal disease (ESRD)." (PMID 34367315, 2021). "Nevertheless, high FGF23 levels are associated with an increased prevalence of LVH in larger pediatric CKD cohorts enrolled in the Chronic Kidney Disease in Children (CKiD) study." (PMID 34536161, 2021). "Fibroblast growth factor-23 (FGF23) and α-klotho are associated with anemia in patients with chronic kidney disease." (PMID 34758731, 2021). "Bone-produced fibroblast growth factor 23 (FGF23) increases in response to inflammation and iron deficiency and contributes to cardiovascular mortality in chronic kidney disease (CKD)." (PMID 34334787, 2021). "Various clinical studies have already shown that elevated FGF23 levels are strongly associated with total and cardiovascular (CV) mortality, especially in patients with chronic kidney disease (CKD)." (PMID 34055103, 2021). "Circulating FGF23 is markedly elevated during chronic kidney disease (CKD), and this is associated with poor long-term outcomes." (PMID 32982979, 2020). "As these patients develop more substantial chronic kidney disease affecting their allografts, fibroblast growth factor 23 (FGF23) increases and is associated with increased cardiovascular and all-cause mortality in kidney transplant recipients." (PMID 32613001, 2020). "Anemia, elevated FGF23, and elevated serum phosphate are significant mortality risk factors for patients with chronic kidney disease (CKD)." (PMID 32476270, 2020). "Multiple studies have shown a strong association between increased FGF23 levels and risk of progression of chronic kidney disease, cardiovascular events and mortality." (PMID 31075857, 2019). "Cross-sectional and population-based prospective studies have showed that FGF23 is a risk factor for low renal function and incident chronic kidney disease." (PMID 31114450, 2019). "Elevated levels of fibroblast growth factor 23 (FGF23) and phosphate are highly associated with increased cardiovascular disease and mortality in patients suffering from chronic kidney disease (CKD)." (PMID 31698866, 2019). "Fibroblast growth factor 23 (FGF23) is associated with left ventricular hypertrophy (LVH) in patients with chronic kidney disease, and calcimimetic therapy reduces plasma concentrations of FGF23." (PMID 31651370, 2019).